TRPS1 (transcriptional repressor GATA binding 1)
Diseases named in the same sentence as TRPS1 in open-access papers (continued):
Sharing a sentence is not in itself a finding about the gene and the disease.
tumor (continued). "To determine the potential function of TRPS1 in vivo, we made use of orthotopic tumor model by injecting Ishikawa, Ishikawa-TRPS1, T47D, T47D-shTRPS1 stable cell lines into nude mice, respectively, and tumor growth was monitored over time." (PMID 37344459, 2023). "The analysis of the transposon integration sites identified several candidate genes, of which Man1a1, Pkp4, Rab10, Rasa1, Trps1, Vps26a, Xpnpep3 and Znf326 accelerated tumor growth, whereas the silencing of R3hcc1l reduced tumor growth." (PMID 36497409, 2022). "TRPS1 was negatively correlated with TGF-β, possibly because TRPS1 suppressed the inhibitory effect of TGF-β during pre-tumor growth." (PMID 35102149, 2022). "Downregulation of Trps1 resulted in the largest acceleration of tumor growth in the functional validation studies, and TRPS1 functions as a tumor suppressor gene in TNBC." (PMID 36497409, 2022). "This bioinformatic analysis process not only identifies MGP and TRPS1 as novel candidate IHC markers to support breast origin but also provides a new approach for the future selection of specific biomarkers in other tumor types." (PMID 36284362, 2022). "In vitro and in vivo experiments demonstrated that silencing TRPS1 inhibited tumor growth, whereas HDAC2 overexpression promoted it." (PMID 35359455, 2022). "TRPS1 and SLC2A1 have previously been implicated in PC and AR action, and decreased EFS expression has been associated with more advanced PC and tumor recurrence." (PMID 33974560, 2021). "Knockdown of Trps1 results in reduced tumor growth in shRNA screens and Trps1 has been shown to repress transcription by interacting with multiple components of the nucleosome remodeling deacetylase complex." (PMID 35087569, 2021). "High TRPS1 activity is associated with decreased YAP activity and leads to decreased frequency of tumour-infiltrating immune cells." (PMID 30082728, 2018). "Nevertheless, our observations extend current knowledge of the importance of TRPS1 function in carcinogenesis by deciphering the TRPS1-UPS4-HDAC2 regulatory axis and uncovering how TRPS1 contributes to tumor growth." (PMID 30071870, 2018). "Consistent with the in vitro experiments, in xenograft mouse models, silencing TRPS1 significantly reduced both tumor volume and weight, and additional overexpression of HDAC2 rescued this phenotype of xenograft tumors." (PMID 30071870, 2018). "Significantly, our results revealed the scaffolding function of TPRS1 in USP4-directed HDAC2 de-ubiquitination and provided new mechanistic insights into the crosstalk between TRPS1, ubiquitin, and histone modification systems leading to tumor growth." (PMID 30071870, 2018). "We reasoned that low activity of TRPS1 in the tumours should lead to upregulation of its repressed genes from the RNA-Seq experiments, whereas high activity of YAP in the tumours should lead to upregulation of the genes identified after YAP 5SA overexpression." (PMID 30082728, 2018). "Previous studies have proved that Trps1 is expressed in several human malignant tumors and implied an important function in tumor growth, invasion, and metastasis." (PMID 26377811, 2015). "Our findings will also help to unravel the oncogenic activity of TRPS1 in cancer development aside from its known role as a tumor suppressor." (PMID 25277197, 2014). "In this study, we sought to ascertain a role for TRPS1 in cellular proliferation and cell cycle in cancer cell lines and tumor samples." (PMID 25277197, 2014). "An increasing number of studies are demonstrating that Trps1 is an indispensable regulator of embryonic development, growth plate regulation, and tumor morphology." (PMID 24709795, 2013). "Adding androgen to the culture medium promotes tumor cell growth and simultaneously represses TRPS1 mRNA expression." (PMID 24709795, 2013). "Here, we will briefly review Trps1 and how it exerts its function in embryonic development and tumor progression by interfering with cell proliferation and death." (PMID 24709795, 2013).
tumor (continued). "There is growing evidence suggesting a multifaceted role for TRPS1 in tumor biology." (PMID 39307879, 2024). "Further research should focus on elucidating the molecular pathways regulating TRPS1 expression in various tumor types, which may better define its clinical utility." (PMID 39518009, 2024). "Tumor heterogeneity may also lead to variable TRPS1 expression within the same lesion, particularly in metastases, where some areas of the tumor may express TRPS1 while others do not." (PMID 39518009, 2024). "The TRPS1 R544Q mutation was compellingly indicated in the single cells from the liver metastasis, but not in cells from the primary tumor or the lymphatic metastasis." (PMID 39307879, 2024). "Likewise, in the T47D-shTRPS1 group, TRPS1 silencing exerted a much stronger inhibitory effect upon tumor growth compared with control group." (PMID 37344459, 2023). "The study found a variable staining expression of TRPS1 in the tumor nests of TB, TE, and BCC." (PMID 37366800, 2023). "We could also see from the tumor growth curve and found that in the Ishikawa-TRPS1 group, tumor growth in nude mice was significantly suppressed after MPA treatment." (PMID 37344459, 2023). "The GATA-type zinc finger transcription factor TRPS1 could function as a novel context-dependent tumor suppressor." (PMID 37344459, 2023). "When TRPS1-overexpressing cells were injected into the mammary fat pad of athymic nude mice, a significant decrease in lung metastatic progression was observed, indicating that TRPS1 is a tumor suppressor gene that inhibits lung metastasis." (PMID 36497409, 2022). "Two gCIS, Nf1 and Trps1, show synthetic haploinsufficient tumor suppressor activity." (PMID 34475389, 2021). "Interestingly, Trps1 is an inhibitor of EMT in tumor and liver cells and Trps1 levels were positively correlated with E-cadherin." (PMID 31130868, 2019). "Furthermore, in vitro cell proliferation assay and in vivo tumor xenografts were used to detect the effect of TRPS1 on tumor growth." (PMID 30071870, 2018). "Our observation that USP4 is recruited by TRPS1 to de-ubiquitinate HDAC2 and silence USP4, resulting in inhibition of tumor cell growth by TRPS1, is consistent with these notions elucidating the underlying molecular details of the oncogenic function of the TRPS1/HDAC2/USP4 axis in tumor growth." (PMID 30071870, 2018). "The oncogenic role of TRPS1, however, might be because of TRPS1's function as a positive regulator of cancer cell proliferation, which will lead to tumor growth." (PMID 25277197, 2014). "When the cut-off level score for TRPS1 to be positive is 1, the TRPS1 was not remarkably associated with the tumour grade, pathological stage, tumour size and lymph node metastasis." (PMID 24934762, 2014). "Collective evidence shows that Trps1 may play a protective role in preventing tumor growth, invasion, and metastasis by promoting apoptosis and counteracting epithelial-mesenchymal transitions." (PMID 24709795, 2013). "Considering that gastric poorly cohesive or Lauren diffuse-type carcinomas often share common morphological and immunohistochemical features with ILC, we believe that TRPS1 may serve as an interesting marker in the differential diagnosis between these two tumor types." (PMID 39449380, 2024). "Furthermore, tumor heterogeneity and pre-analytical variables can complicate the interpretation of weak or negative staining, underscoring the importance of using TRPS1 in conjunction with other diagnostic markers." (PMID 39518009, 2024). "Thus, TRPS1 was deemed to be a powerful alternative target for tumor inhibition, and the dysregulation of TRPS1 may be a mechanism involved in tumorigenesis." (PMID 36238488, 2022). "Thus, we have assumed that TRPS1 might transcriptionally both regulate genes and affect tumour growth and development to varying degrees." (PMID 24934762, 2014).
tumor (continued). "The tumor cells were positive for GATA3, TRPS1, E-cadherin and the neuroendocrine markers Syn and insulinoma associated protein 1 (INSM1)." (PMID 40994809, 2025). "TRPS1, a GATA family transcriptional regulatory factor, has been shown to induce tumor angiogenesis, affect VEGFA expression, and promote tumor cell proliferation in tumors." (PMID 37745301, 2023). "We propose a diagnostic strategy using highly sensitive markers including TRPS1, INSM1, and P16 expression, as well as HPV and EBER testing for identification of primary tumor sites in clinical practice." (PMID 38041048, 2023). "In summary, the recruitment of cofactor TRPS1 by the activated PR differently altered the acetylation level of RANKL via establishing the PR/TRPS1/HDAC2 complex in EC and BC, thus affecting tumor behaviors." (PMID 37344459, 2023). "It is involved in the regulation of multiple tumor signaling pathways, such as PI3K/AKT, PTEN, JAK/STAT, TRPS1/ZEB1 and EMT." (PMID 35054253, 2021). "Meanwhile, tumor suppressors, including KLF12, PRKG1, TRPS1, NOTCH1, RORA, were downregulated in the HSPA8high group." (PMID 33926391, 2021). "We also observed that tumor suppressors, including KLF12, PRKG1, TRPS1, NOTCH1, and RORA, were downregulated in the HSPA8high group." (PMID 33926391, 2021). "These scenarios fit well with our working model that TRPS1 recruits USP4 to stabilize HDAC2 and represses expression of AES, Casp7, PERP, and ZW10 to confer tumor growth." (PMID 30071870, 2018). "Our working model suggests that TRPS1 recruits USP4 to stabilize HDAC2 repressing the expression of AES, Casp7, PERP, and ZW10 to confer tumor growth." (PMID 30071870, 2018). "Taken together these results led to a mechanistic scheme in which TRPS1 scaffolding recruits USP4 to de-ubiquitinate and stabilize HDAC2, leading to repression of a set of anti-growth genes and acceleration of tumor growth." (PMID 30071870, 2018). "Nevertheless, our observation that TRPS1 recruits USP4 to de-ubiquitinate HDAC2 extends the current knowledge on the regulation of HDAC2 stability by the ubiquitin system, contributing to tumor growth." (PMID 30071870, 2018). "In vitro and in vivo experiments confirmed that silencing TRPS1 reduced tumor growth, whereas overexpression of HDAC2 restored tumor growth." (PMID 30071870, 2018). "Survival analysis indicated TRPS1 high expression was significantly associated with better RFS in all BC patients, hormone sensitive and Her-2 positive BC, but not in ER negative, Her-2 negative or basal-like subtypes, which implied that TRPS1 might act as a tumor suppressor in BC." (PMID 28423734, 2017). "Many studies have confirmed that Trps1, a GATA family transcriptional factor, is involved in the regulation of EMT, and plays important roles in embryonic development and tumor metastasis." (PMID 25886207, 2015). "miR-221/222 act on its downstream target, trichorhinophalangeal syndrome type 1 (TRPS1), which is an inhibitor of EMT, and miR-221/222 can reduce its expression, thus promoting the epithelial–mesenchymal transition of tumor cells and increasing tumor invasion." (PMID 40821785, 2025). "Noteworthy discrepancies were observed in individual cases, such as case 26, where all readers deemed the tumor positive, yet it exhibited no TRPS1 expression upon relapse." (PMID 38902365, 2025). "Conversely, in case 27, while the primary tumor showed no TRPS1 labeling, its metastasis to the contralateral breast displayed full positivity for TRPS1." (PMID 38902365, 2025). "An intriguing case in our study involved an AS with a corresponding local relapse, where unexpectedly, the primary tumor was identified as positive for TRPS1, while all readers considered the relapse negative." (PMID 38902365, 2025).
tumor (continued). "Our study did not include this tumor type in our cohort; however, a recent study emphasized that TRPS1 is frequently expressed in SSs." (PMID 39051323, 2024). "Our study suggests that TRPS1 may provide only limited benefit to differentiating TB and TE from BCC, due to the variable staining patterns in the tumor nests and patchy staining patterns." (PMID 37366800, 2023). "TRPS1 highlighted perifollicular mesenchymal cells adjacent to the nests of TB and TE tumor cells, while the uninvolved dermis was negative." (PMID 37366800, 2023). "In this study, we report that TRPS1, USP4, and HDAC2 form a regulatory axis to confer tumor growth." (PMID 30071870, 2018). "Indeed, TRPS1 and Cath-D co-repress transcription of secreted protein rich in cysteine gene (SPARC), a tumor suppressor in MDA-MB-231 ER− BCC and promote c-MYC and TGFB3 expression." (PMID 26183398, 2015). "In the analysis of a 180-member TMA, we found positive TRPS1 expression in 93 cases (51.7%), while 87 tumours (48.3%) were negative." (PMID 24934762, 2014). "In the immunohistochemical analysis, the tumor cells were positive for GATA-binding protein 3 (GATA3) and trichorhinophalangeal syndrome type 1 (TRPS1) but negative for HepPar1 and Glypican-3, which indicated that the tumor originated in the breast rather than the liver." (PMID 40994809, 2025). "Using TRPS1 activity score to classify patients may provide additional insight into the transcriptional program within a patient’s tumor that might not be immediately apparent based on previous surrogates for TRPS1 activity." (PMID 38377146, 2024). "While TRPS1 IHC staining within the tumor nests might not be especially helpful in distinguishing BCC from TB and TE, a characteristic stromal staining pattern was apparent." (PMID 37366800, 2023). "In EC, upon MPA treatment, TRPS1 could act as a transcription corepressor and interact with HDAC2 to form a PR/TRPS1/HDAC2 complex to deacetylate RANKL, downregulating the expression of RANKL and thereby exerting an anti-tumor effect." (PMID 37344459, 2023). "We have not investigated other tumour types; therefore, the specificity of TRPS1 could not be determined directly, but on the basis of the limited data available, this is also a rather specific marker." (PMID 37012444, 2023). "On the other hand, TRPS1 showed no or little expression in other tumor types." (PMID 36284362, 2022). "Interestingly, we have identified several transcription factors like TRPS1, NFAT5, FoxF2, ELF4, RLF etc. which haven’t previously been reported to be involved in PDAC but shown to induce EMT, angiogenesis or proliferation of tumours in other organs." (PMID 31795960, 2019). "Even though Trps1 depletion had no measurable effect on cell proliferation in vitro, Trps1-depleted 4T1 cells demonstrated a strongly impaired tumour growth in vivo." (PMID 30082728, 2018). "Therefore, the absence of TRPS1 expression does not exclude a breast origin for the tumor." (PMID 40822238, 2025). "Although TRPS1 is not absolutely specific or sensitive to a particular primary, we consider that it can be added to a panel of other markers when investigating the origin of a cutaneous metastasis, namely when this is the first manifestation of the neoplastic disease." (PMID 39449380, 2024). "Immunohistochemically, the tumor exhibited diffuse positivity for CD31 and ERG, with no discernible expression of MYC and negativity for TRPS1." (PMID 38902365, 2025). "If CDX2 and SATB2 are both negative, or if CK7 is positive but CK20 and TRPS1 are negative, third-tier immunostains including p63, GATA3, uroplakin II/III, PSA, and NKX3.1 should be performed to further classify the tumor as urothelial or prostatic secondary EMPD." (PMID 41463263, 2025).
cancer (39 papers, 2010 to 2025). A tumor composed of atypical neoplastic, often pleomorphic cells that invade other tissues. "The ongoing refinement of TRPS1 IHC and exploration of its broader applications can enhance diagnostic accuracy and support more personalized, effective cancer care." (PMID 39518009, 2024). "In the present study, we demonstrate that elevated TRPS1 expression in BC cells is a causal factor in protecting cancer cells from the cytotoxicity of chemotherapy." (PMID 39276941, 2024). "Given that TRPS1 mutations have been previously reported in human cancers and associated with metastasis, TRPS1 was singled out as a candidate gene for additional investigation into the molecular mechanisms responsible for distant metastasis in CRC." (PMID 39307879, 2024). "On IHC level they found that although TRPS1 and GATA3 expression were comparable in hormone-positive and HER2neu-positive cancers, however the expression of TRPS1 was higher in TNBC, particularly metaplastic carcinoma compared with GATA3 (86% vs. 21%)." (PMID 40025593, 2025). "In this study, we determined the primary origin of cancer via both morphologic correlations, IHC workup and molecular analysis (in some cases) and then compared the sensitivity and specificity of TRPS1 with other commonly used breast-specific markers." (PMID 40025593, 2025). "Our study demonstrated a higher sensitivity of TRPS1 in establishing carcinoma of breast origin compared with GATA3 and SOX10, consistent with previous reported studies." (PMID 40025593, 2025). "The sensitivity and specificity of TRPS1 in determining carcinoma of breast origin were compared with those of GATA3 and SOX10." (PMID 40025593, 2025). "Our study demonstrated a higher sensitivity of TRPS1 expression in establishing carcinoma of breast origin compared with GATA3 and SOX10, consistent with previous reported studies." (PMID 40025593, 2025). "TRPS1 R544Q mutant cells significantly accelerate cancer cell migration and invasion both in vitro and in vivo." (PMID 39307879, 2024). "Understanding the broader expression of TRPS1 can help to improve cancer diagnosis and treatment strategies." (PMID 39518009, 2024). "They performed CRISPR-Cas9 screening in vivo and identified Trps1 as a master regulator of ectopic cancer growth using CRISPR knockout screening." (PMID 38474078, 2024). "Using data from the Cancer Dependency Map project, we found that sensitivity to TRPS1 knockout correlated with sensitivity to knockout of ESR1, the gene encoding ER." (PMID 38377146, 2024). "In cancer cells, TRPS1 recruits repressor complexes to enhancer sites which is critical for cancer cell proliferation." (PMID 38702730, 2024). "Taken together, these data suggest a model in which TRPS1 modulates the genomic distribution of ER, both activating and repressing transcription of genes related to cancer cell fitness." (PMID 38377146, 2024). "How TRPS1 becomes an oncogene and how it can be targeted most efficiently needs to be addressed in the future and will require the generation of adapted mouse models combining cancer model and shRNA based Trps1 depletion." (PMID 38702730, 2024). "Taken together, these data suggest a model in which TRPS1 modulates the activity of other TFs, both activating and repressing transcription of genes related to cancer cell fitness." (PMID 37461612, 2023). "Our data provide a mechanistic link between TRPS1, the ubiquitin system, and the histone modification system in cancer by revealing the TRPS1-USP4-HDAC2 regulatory axis that is involved in tumor growth." (PMID 30071870, 2018). "Transcriptional repressor GATA binding 1 (TRPS1), an atypical GATA transcription factor, functions as a transcriptional repressor and is also implicated in human cancers." (PMID 30563971, 2018). "Consistently, in another dataset from Sorlie's study, TRPS1 was 2.338 fold increased in cancer VS. normal samples (p=0.001)." (PMID 28423734, 2017).